PPM1N (protein phosphatase, Mg2+/Mn2+ dependent 1N (putative))
Synonyms: FLJ40125
Tractability: PROTAC: its protein half-life has been measured.
Gene: Protein-coding gene on chromosome 19 (45,488,777 to 45,503,129, forward strand). Ensembl gene ENSG00000213889.
Subcellular location (Human Protein Atlas): Vesicles
Gene Ontology:
Molecular function: magnesium ion binding; manganese ion binding; phosphoprotein phosphatase activity; protein serine/threonine phosphatase activity
Biological process: positive regulation of canonical Wnt signaling pathway; regulation of canonical NF-kappaB signal transduction
Cellular component: cytosol; nucleus
Genetic constraint (gnomAD): Loss-of-function variants: 35 observed, 22.62 expected, observed/expected ratio (o/e) 1.55, 90% interval 1.17 to 1.91. The synonymous counts are far from expectation, so gnomAD's model fits this gene poorly and the ratio says little. Missense variants: 648 observed, 477.77 expected, observed/expected ratio (o/e) 1.36, 90% interval 1.27 to 1.45. Synonymous variants: 275 observed, 211.22 expected, observed/expected ratio (o/e) 1.3, 90% interval 1.18 to 1.44.
Homologues: Orthologues: chimpanzee PPM1N (99% identical), macaque PPM1N (93% identical), pig PPM1N (79% identical), dog PPM1N (79% identical), mouse Ppm1n (70% identical), guinea pig PPM1N (64% identical), rat Ppm1n (64% identical), rabbit PPM1N (59% identical), zebrafish ppm1nb (38% identical), zebrafish ppm1na (35% identical), Drosophila melanogaster alph (33% identical), Drosophila melanogaster Nil (31% identical), and 12 more. Paralogues in human: PPM1B (39% identical), PPM1A (39% identical), PPM1G (27% identical), PPM1E (25% identical), PPM1F (24% identical), PPM1D (22% identical), PPM1H (21% identical), PDP1 (20% identical), PPM1M (20% identical), PDP2 (20% identical), PPM1K (20% identical), PPM1L (20% identical), and 4 more.
Diseases named in the same sentence as PPM1N in open-access papers:
PPM1N is named in the same sentence as 3 diseases in open-access papers, as found by Europe PMC text mining. Sharing a sentence is not in itself a finding about the gene and the disease. The quoted sentences say what the papers report.
pterygium (1 paper, 2021). A wedge-shaped fibrovascular lesion arising from the bulbar conjunctiva and extending to the cornea. "PPM1N, which encodes a phosphatase, was one of the top upregulated DEGs in pterygium." (PMID 34769520, 2021). "This analysis suggests increased activity of the Notch and Wnt epithelial differentiation pathways in pterygium, and identifies HES5, WNT7B, WNT9A, and PPM1N as being specifically involved." (PMID 34769520, 2021). "Our further analysis of pathways controlled by upstream regulator TP63 suggested increased activity of the Notch and Wnt epithelial differentiation pathways in pterygium, and identified WNT7B, WNT9A, PPM1N and HES5 as likely involved." (PMID 34769520, 2021).
PPM1N also shares sentences with these, for which no sentence is quoted: asthma (1 paper); chronic obstructive pulmonary disease (1).